TET2 (tet methylcytosine dioxygenase 2)
Diseases named in the same sentence as TET2 in open-access papers (continued):
Sharing a sentence is not in itself a finding about the gene and the disease.
liver cancer (6 papers, 2017 to 2024). An epithelial or non-epithelial malignant neoplasm that arises from the liver. "We further verified the regulation of tumor cGAS by TET2 and STAT5A signaling in human liver cancer samples and found that high tumor TET2 and p-STAT5A expressions were associated with high tumor cGAS expression." (PMID 38177099, 2024). "Collectively, these data show that tumor TET2-p-STAT5A-cGAS-LRRC8C-endothelial STING axis is linked to vascular normalization and immune infiltration in human liver cancer." (PMID 38177099, 2024). "Tet2 blockade by either Tet2 knockdown or Tet enzyme inhibitor (cell-permeable 2-hydroxyglutarate (2-HG)) significantly decreased VC-induced Cgas expression in liver cancer cells." (PMID 38177099, 2024). "Together, these findings provide conclusive evidence for the crucial involvement of tumor Tet2 and Stat5a in VC-mediated vascular normalizing effects and the combinational efficiency of VC and anti-PD-L1 therapy in liver cancer." (PMID 38177099, 2024). "Expectedly, we further demonstrate that as a TETs enzyme activator, VC treatment increases cGAS expression via TET2-dependent demethylation in liver cancer cells." (PMID 38177099, 2024). "Next, we investigated the protein expression levels of tumor TET2-p-STAT5A-cGAS-LRRC8C-endothelial STING axis in tumor biopsies from liver cancer patients." (PMID 38177099, 2024). "Together, these findings suggest that TET2 is a major mediator of cGAS expression in liver cancer." (PMID 38177099, 2024). "To further investigate whether TET2 regulates cGAS expression, we overexpressed Tet1, Tet2, and Tet3 in liver cancer cells, respectively." (PMID 38177099, 2024). "To confirm this hypothesis, we conducted WDR24, a component of GATOR2, and TET2 single/double KO in liver cancer cells and examined their effects on mTORC1 activity and tumor growth using xenograft model." (PMID 37550284, 2023). "Here the authors show that TET2 upregulates tumor cGAS to activate STING in endothelial cells, inducing tumor vascular normalization and enhancing efficacy of anti-PD-L1 alone or combined with IL-2 in liver cancer preclinical models." (PMID 38177099, 2024). "In vitro, disruption of Stat5a, but not Stat1, which exhibited a positive correlation with cGAS regardless of TET2 expression, impaired Cgas expression in liver cancer cells." (PMID 38177099, 2024).
lymph node metastasis (6 papers, 2015 to 2024). "Univariate analysis showed that TET2/5hmC association (P < 0.001), differentiation (P = 0.036), lymph node metastasis (P = 0.015), and FIGO stage (P = 0.006) were significantly related to overall survival of EC patients." (PMID 38515066, 2024). "The results showed that TET2/5hmC association was significantly associated with differentiation (χ2 = 82.249, P < 0.001), myometrial invasion (χ2 = 44.060, P < 0.001), lymph node metastasis (χ2 = 15.231, P = 0.002), and FIGO stage (χ2 = 38.769, P < 0.001)." (PMID 38515066, 2024). "Multivariate Cox regression analysis revealed that stage, lymph node metastasis, and TET2 expression were associated with prognosis in patients with endometrial adenocarcinoma (P < 0.05)." (PMID 35480097, 2022). "Multivariate analysis further demonstrated TET2/5hmC association (HR: 2.843; 95%CI: 1.226–3.605; P = 0.007), lymph node metastasis (HR: 5.241; 95%CI: 1.169–13.856; P = 0.037), and FIGO stage (HR: 3.979; 95%CI: 2.153–6.780; P = 0.023) were independent prognostic factors for EC patients." (PMID 38515066, 2024). "Further multivariate analysis revealed the association of TET2 and 5hmC, FIGO stage, and lymph node metastasis were independent factors affecting EC prognosis." (PMID 38515066, 2024). "In a study, Zhang reported that TET2 expression in OV was significantly lower than that in normal ovarian tissues and was correlated with the pathologic stage, tumor grade, lymph node metastasis, and vascular thrombosis, which is consistent with our findings." (PMID 35223782, 2022).
myeloma (6 papers, 2013 to 2025). "In myeloma patients, DNMT3A mutations were present with a VAF range of 2–19%, and TET2 mutations with a VAF range of 14% to 54%." (PMID 40869343, 2025). "The multi-fractal property of myeloma multiple TET2 mRNA Variant1 and Variant2 has been shown to converge to 1.26 in fractal dimension." (PMID 23586047, 2013).
non-small cell lung carcinoma (6 papers, 2019 to 2025). A group of at least three distinct histological types of lung cancer, including non-small cell squamous cell carcinoma, adenocarcinoma, and large cell carcinoma. "Additionally, TET2 has been identified as a key player in the resistance mechanisms of various cancers, such as non-small cell lung cancer, suggesting that drugs aimed at restoring TET2 function could be effective in overcoming therapeutic resistance." (PMID 41169875, 2025). "In this study, we demonstrate a tumour suppressor role of TET2 in LUAD, providing new potential molecular therapeutic targets and clinical therapies for patients with non-small cell lung cancer." (PMID 37667220, 2023).
renal carcinoma (6 papers, 2018 to 2024). A carcinoma arising from the epithelium of the renal parenchyma or the renal pelvis. "The present study demonstrated that ascorbic acid enhanced the efficacy of immunotherapy and that the loss of TET2 function enabled renal cancer cells to evade antitumor immunity." (PMID 35173532, 2022). "Studies have also shown that TET2 suppresses glycolytic capability in renal carcinoma by downregulating FBP1 expression." (PMID 38238754, 2024). "Other gene mutations, such as FANCD2, FAT3, KDM6A, KDR, TET2, and TSC2, occurred twice in this MA cohort, which was quite different from other common types of renal carcinoma." (PMID 30111351, 2018). "In addition, FCM results showed that renal cancer cells co‐expressing TET2 and CD44 accounted for 1.82 ± 0.15% of the entire cell population." (PMID 30411496, 2019).
rheumatoid arthritis (6 papers, 2021 to 2025). A chronic, systemic autoimmune disorder characterized by inflammation in the synovial membranes and articular surfaces. "This study elucidates that TNF-α drives macrophage-derived itaconate production to epigenetically suppress osteoclast hyperactivation through Tet2 inhibition, establishing itaconate and its derivative OI as novel therapeutic agents against rheumatoid arthritis -associated bone destruction." (PMID 40500265, 2025). "Rheumatoid arthritis (RA) patients also demonstrate an elevated CHIP prevalence, especially in older patients, with DNMT3A and TET2 mutations prevalent." (PMID 39997650, 2025). "Similarly, rheumatoid arthritis (RA) patients have a 17% higher prevalence of CHIP, which increases to 25% in individuals aged 70-79 years, with DNMT3A and TET2 mutations being the most frequent." (PMID 38162500, 2023). "Additionally, osteoclast activation is related to rheumatoid arthritis (RA); Tet2 can contribute to osteoclast differentiation and suppress inflammation, and a relationship between Tet2 and RA has been established." (PMID 34222235, 2021).
Sepsis (6 papers, 2021 to 2025). Sepsis is defined as life-threatening organ dysfunction caused by a dysregulated host response to infection. "Overall, we demonstrate that Tet2 mutations drive known sepsis features, such as cytokine-driven hyperinflammatory response and immunosuppression, characterized by reduced activity of phagocytes." (PMID 38573824, 2024). "We observed reduced Tet2 expression in IR, renal transplant, and sepsis mice models at different time points, suggesting a possible important role of Tet2 in AKI caused by other reasons." (PMID 34226503, 2021). "Beyond oxidation of methylated cytosine in DNA, TET2 has also been reported to promote mRNA oxidation during infection derived sepsis, thereby destabilizing target mRNA; TET2 can suppress expression of endogenous retroviruses through a similar mechanism." (PMID 34394088, 2021). "In an earlier study, global Tet2-knockout and control mice showed similar bacterial loads during polymicrobial sepsis induced by cecal ligation and puncture." (PMID 35011643, 2021). "The presence of TET2 impaired survival in mice with sepsis by promoting emergency myelopoiesis and a cytokine storm through oxidation of 5-mC in Socs3 mRNA resulting in destabilization of this mRNA." (PMID 34394088, 2021). "TET2 promotion of sepsis has been shown to occur due to TET2 suppression of Soc3 expression." (PMID 41013544, 2025). "Of note, these two previous investigations made use of mice with a global Tet2 deficiency; thus far mice with a myeloid cell-specific Tet2 deletion have not been studied in conditions relevant for infection or sepsis." (PMID 35011643, 2021). "TET2 expression was increased in blood leukocytes during sepsis." (PMID 35011643, 2021). "Therefore, succinate and itaconate could contribute to the reduction of sepsis by regulating TET2." (PMID 41013544, 2025).
Thrombocytopenia (6 papers, 2021 to 2025). A reduction in the number of circulating thrombocytes. "TET2 mutations, present in 34% of NK-LGLL cases, correlate with thrombocytopenia and co-occurrence of a other hematologic malignancies." (PMID 40895526, 2025). "Thrombocytopenia was positively correlated with U2AF1 and MPL, whereas thrombocytopenia was negatively correlated with the TET2 mutations." (PMID 36139644, 2022). "In addition, we observed normalization of leukocytosis, monocytosis, and thrombocytopenia in Tet2/Stag2-mutant mice treated with talazoparib, which was associated with increased numbers of megakaryocytes on blinded review (P = 0.007)." (PMID 33351783, 2021).
aortic valve stenosis (5 papers, 2020 to 2025). Aortic valve stenosis (AVS) is a condition characterized by narrowing of the heart's aortic valve opening. "Mutations in the clonal hematopoiesis of indeterminate potential (CHIP)-driver genes DNMT3A and TET2 have been previously shown to be associated with short-term prognosis in patients undergoing TAVR for aortic valve stenosis." (PMID 36680616, 2023). "DNMT3A- and TET2-CHIP-driver mutations are associated with long-term mortality in patients with aortic valve stenosis even after a successful TAVR." (PMID 36680616, 2023).
chronic obstructive pulmonary disease (5 papers, 2020 to 2025). A chronic and progressive lung disorder characterized by the loss of elasticity of the bronchial tree and the air sacs, destruction of the air sacs wall, thickening of the bronchial wall, and mucous accumulation in the bronchial tree. "Tobacco smoke has also been found to promote the expansion of TET2-mutated blood cells, potentially acting as a contributing factor to chronic obstructive pulmonary disease (COPD)." (PMID 38162500, 2023). "Individuals with somatic variants in TET2 were found to have an elevated prevalence of self-reported asthma or chronic obstructive pulmonary disease (COPD), though the nature of this relationship is unclear." (PMID 31963585, 2020). "In a mouse model of chronic obstructive pulmonary disease (COPD), the deletion of DNA dioxygenase ten-eleven translocation 2 (TET2) triggered ferroptosis and further exaggerated cigarette smoke (CS)-induced inflammation." (PMID 39769377, 2024). "Our findings are consistent with the notion that CH with TET2 mutations is different from CH with DNMT3A or ASXL1 mutations as indicated by some clinical studies, for example, CH with TET2 mutations has been linked to chronic obstructive pulmonary diseases but not CH with DNMT3A mutations." (PMID 37083525, 2023).
esophageal squamous cell carcinoma (5 papers, 2016 to 2022). Esophageal squamous cell carcinoma (ESCC) is a type of esophageal carcinoma (EC) that can affect any part of the esophagus, but is usually located in the upper or middle third. "TET2 expression was significantly lower in esophageal squamous cell carcinoma and associated with 5hmC levels." (PMID 29849955, 2018). "TET2 expression is also significantly associated with 5-hmC levels in esophageal squamous cell carcinoma." (PMID 27129173, 2016). "It was recently reported that TET2 expression is lower in esophageal SCC than in normal epithelium and associated with 5-hmC expression; it was speculated that TET2 is more significant in esophageal SCC development than TET1 and TET3." (PMID 28616099, 2017).
essential thrombocythemia (5 papers, 2012 to 2020). A chronic myeloproliferative neoplasm that involves primarily the megakaryocytic lineage. "Third, we still miss information in some diseases such as essential thrombocythemia (ET), in which JAK2 mutations are found in only half the cases, and TET2 mutations in less than 10%." (PMID 22823977, 2012).
Hepatic steatosis (5 papers, 2020 to 2025). Steatosis is a term used to denote lipid accumulation within hepatocytes. "Given the previous finding that TET2 and TET3 liver specific KO promoted fatty liver development in mice, we decided to investigate the role of TET1 in hepatic steatosis." (PMID 40164757, 2025).
pneumonia (5 papers, 2021 to 2025). An acute, acute and chronic, or chronic inflammation focally or diffusely affecting the lung parenchyma, caused by an infection in one or both of the lungs (by bacteria, viruses, fungi, or mycoplasma.). "The subgroup with TET2 mutations had higher incidence of death due to pneumonia or lung disease, which was theorized to be secondary to a maladapted innate response to infection, as TET2 mutated mature myeloid cells have pro-inflammatory features." (PMID 40361435, 2025). "Taken together, these results indicate that Tet2 deficiency confers an inappropriate and pathological myeloid cell response in pneumonia." (PMID 38573824, 2024). "We recently reported on the role of Tet2 in bronchial epithelial cells in maintaining barrier integrity during pneumonia caused by Pseudomonas." (PMID 35011643, 2021).
adult T-cell leukemia/lymphoma (4 papers, 2017 to 2022). A peripheral (mature) T-cell neoplasm linked to the human T-cell leukemia virus type 1 (HTLV-1), adult T-cell leukemia/lymphoma is endemic in several regions of the world, in particular Japan, the Caribbean, and parts of Central Africa. "Adult T-cell leukemia/lymphoma (ATLL) progression accompanies genomic 5hmC loss, suggesting that Tet2 downregulation is the vital mechanism underlying 5hmC regulation during ATLL progression." (PMID 33184433, 2020). "Mutations in TET2, encoding one of the TET members responsible for the conversion of DNA cytosine methylation to hydroxymethylation (5-hmc), have been recently described in Human T-lymphotropic virus type 1-associated adult T-cell leukemia/lymphoma (ATLL)." (PMID 28881727, 2017).
aortic stenosis (4 papers, 2020 to 2025). Aortic valve stenosis is a aortic valve disease caused by the incomplete opening of the aortic valve. "In conclusion, carrying a DNMT3A- and/or TET2-CHIP-driver mutation is an independent prognostic risk factor for increased long-term mortality in patients with severe aortic stenosis even after successful removal of the stenotic valve by TAVR." (PMID 36680616, 2023). "The study enrolled 279 aortic stenosis patients of which 93 (33%) had mutations in DNMT3A or TET2, the two most common CHIP-driver genes." (PMID 32748835, 2020). "Thus, carrying a DNMT3A- or TET2-CHIP-driver mutation appears to be an independent risk factor for worse clinical outcome in patients with severe aortic stenosis even after removal of the stenotic valve by TAVR." (PMID 36680616, 2023). "While the prevalence of DNMT3A- and/or TET2-CHIP-driver mutations remained similar with 32.7%, the association of CHIP with mortality was even stronger in patients with severe aortic stenosis undergoing TAVR, who never smoked." (PMID 36680616, 2023).
aplastic anemia (4 papers, 2019 to 2024). Anemia resulting from bone marrow failure (aplastic or hypoplastic bone marrow). "However, consistent with the durable, unique clinical response of Epag in aplastic anemia, TET2 inhibition may be a key mechanism of action that contributes to a prolonged expansion of HSPCs, leading to complete response and recovery." (PMID 35085104, 2022). "Several TPO-R agonists demonstrate similar hematopoietic activities in aplastic anemia, including TPO peptide mimetic romiplostim, which does not inhibit TET2." (PMID 35085104, 2022).
atrial fibrillation (4 papers, 2024). A disorder characterized by an electrocardiographic finding of a supraventricular arrhythmia characterized by the replacement of consistent P waves by rapid oscillations or fibrillatory waves that vary in size, shape and timing and are accompanied by an irregular ventricular response. "Atrial fibrillation (ICD10 code I48) was associated with rare variation in 8 genes (TTN, RPL3L, KLF1, TET2, NME3, KDM5B, PKP2, PMVK)." (PMID 38390584, 2024). "Another interesting finding is the link between atrial fibrillation and rare variations in the TET2 gene." (PMID 38390584, 2024). "Atrial fibrillation was associated with rare variations in 8 genes (TTN, RPL3L, KLF1, TET2, NME3, KDM5B, PKP2, PMVK)." (PMID 38390584, 2024). "Recent studies investigated the relationship between clonal hematopoiesis of indeterminate potential (CHIP), specifically TET methylcytosine dioxygenase 2 (TET2) CHIP, and atrial fibrillation (AF) in the UK Biobank, finding a modest association." (PMID 39594530, 2024).
cervical squamous cell carcinoma (4 papers, 2016 to 2025). A squamous cell carcinoma arising from the cervical epithelium. "TET2 was decreased in cervical squamous cell carcinoma along with %5-hmC, and low levels in patients were shown to be associated with a poor prognosis." (PMID 27980696, 2016).
osteoporosis (4 papers, 2019 to 2026). A condition of reduced bone mass, with decreased cortical thickness and a decrease in the number and size of the trabeculae of cancellous bone (but normal chemical composition), resulting in increased fracture incidence. "Instead, as demonstrated in tet1 and tet2 knockout mice, it was likely that during aging the osteopenic phenotype is ascribable to a hypermethylation in Tet1 and Tet2 that leads osteoporosis by inhibiting the expression of Runx2." (PMID 37190071, 2023). "Moreover, TET2 is upregulated during hADSC osteogenesis, while inhibition of TET2 reduces osteogenic-related gene expression and 5hmC levels, potentially compromising bone health and contributing to osteoporosis." (PMID 41005477, 2025). "Moreover, both TET1 and TET2 transcript levels were shown to be downregulated during osteoporosis." (PMID 30606231, 2019). "Moreover, we discovered that the expression of TET1 and TET2 is grossly deregulated in osteoporosis leading to deregulated 5hmC levels on promoters of genes controlling stem cell renewal and lineage determination in osteoporosis." (PMID 30606231, 2019). "Finally, in a mouse model of ovariectomy-induced osteoporosis, the numbers of clonogenic BMSC were dramatically diminished corresponding to lower trabecular bone volume and reduced levels of TET1, TET2 and 5hmC." (PMID 30606231, 2019). "Given that both TET1 and TET2 are severely reduced in osteoporosis, pharmacological re-induction of TET1/TET2 may be of therapeutic benefit to individuals suffering from age-related bone loss or osteoporosis." (PMID 30606231, 2019).